ENSG00000284989 (novel transcript)
Gene: Protein-coding gene on chromosome 1 (43,650,149 to 43,931,014, forward strand). Ensembl gene ENSG00000284989.
Genetic constraint (gnomAD): Missense variants: 175 observed, 280.28 expected, observed/expected ratio (o/e) 0.62, 90% interval 0.55 to 0.71. Synonymous variants: 84 observed, 95.72 expected, observed/expected ratio (o/e) 0.88, 90% interval 0.74 to 1.05.